MIR765 (microRNA 765)
Synonyms: hsa-mir-765; MIRN765; mir-765
Gene: MicroRNA gene on chromosome 1 (156,936,131 to 156,936,244, reverse strand). Ensembl gene ENSG00000211581.
Gene Ontology:
Biological process: miRNA-mediated post-transcriptional gene silencing
Diseases named in the same sentence as MIR765 in open-access papers:
MIR765 is named in the same sentence as 2 diseases in open-access papers, as found by Europe PMC text mining. Sharing a sentence is not in itself a finding about the gene and the disease. The quoted sentences say what the papers report.
glioblastoma (1 paper, 2021). The most malignant astrocytic tumor (WHO grade IV). "We found previously uncharacterized miRNA genes in pediatric CNS tumors, including MIR149, MIR214, MIR574 and MIR765, apart from one study that reported MIR595 upregulation in glioblastoma compared to control cells, in vitro." (PMID 34204289, 2021).
CNS tumors (1 paper, 2021). "In cluster 2, MIR149, MIR214, MIR574, MIR595 and MIR765 were globally down-regulated across all CNS tumor samples; ten miRNA genes were also found globally down-regulated in >90% of all samples." (PMID 34204289, 2021).